EZR (ezrin)
Diseases named in the same sentence as EZR in open-access papers (continued):
Sharing a sentence is not in itself a finding about the gene and the disease.
tumor (continued). "Ezrin expression could be evaluated in 263/272 primary and all 28 recurrent tumours." (PMID 25278252, 2014). "Moreover, syngeneic tumours derived from ezrin-deficient or Y477F ezrin-expressing (non-phosphorylatable by Src) AC2M2 cells further confirmed the xenograft results." (PMID 25231728, 2014). "Analysis of ezrin and moesin protein expression and patient clinicopathological parameters revealed significant correlations between protein expression and the presence of lymph node metastases in the tumour compartments (P = 0.047 and P = 0.038, respectively)." (PMID 23420497, 2013). "Moreover, pY477 of ezrin may act via pathways that connect Src to receptor tyrosine kinases such as Met, resulting in invasive properties of tumor cells." (PMID 22397367, 2012). "Moreover, over-expression of Y477F ezrin inhibits local tumor invasion in vivo." (PMID 22397367, 2012). "However the role of ezrin phosphorylation on tyrosine 477 in tumor progression and metastatic dissemination remains unknown." (PMID 22397367, 2012). "Hence, those tumours found to overexpress that ezrin should be monitored closely postoperatively." (PMID 22736953, 2012). "However, the mechanisms of ezrin-mediated tumor development still require further elucidation." (PMID 20569470, 2010). "Taken together, it was found that these tumor suppressor/susceptibility genes can regulate key molecules involved in cell signal pathways such as ras/MEK/ERK, Rb/E2F and EGFR ras/MEK/MAPK, and can regulate the expression of some adhesion molecules such as ezrin, nm23 and α-catenin." (PMID 19949542, 2009). "In our tumor epithelial dataset, genes with the strongest positive correlation with TM4SF1 expression within the HV tumor cells were EMP1, CLDN4, EZR, and KRT19." (PMID 40527915, 2025). "NR4A3 functions as a tumor suppressor in BLCA by enhancing endoplasmic reticulum stress and inhibiting anoikis resistance through the EWSR1/Ezrin pathway." (PMID 40762284, 2025). "Ezrin expression was also significantly elevated in IBC-NST, with higher H score values correlating with high tumor grade (p = 0.002), high N stage (p = 0.045), advanced AJCC stage grouping (p = 0.0043) and metastasis (p = 0.001)." (PMID 39827339, 2025). "Aside from the important roles of Ezrin on driving tissue morphogenesis, promoting tumor invasion, EMT and metastasis, the effects of Ezrin on angiogenesis were also paid much attention." (PMID 38577590, 2024). "However, the absence of CD45 expression, along with the presence of ezrin—a marker more commonly associated with tumor cells—strongly supports the hypothesis that these cells are indeed CTCs." (PMID 39791707, 2024). "Ezrin belongs to the ezrin, radixin, moesin (ERM) protein family and has a demonstrated role as a driver of tumour progression and metastatic spread whose high expression correlates with unfavourable clinical outcome in different cancer types." (PMID 37629086, 2023). "PODXL regulates epithelial and tumor cell motility through interactions with the actin polymerization complexes, including the ERM (ezrin–radixin–moesin) family and PDZ protein Na+/H+ exchanger regulatory factors 1 and 2 (NHERF-1/2)." (PMID 38203331, 2023). "In contrast, the overexpression of T567D Ezrin promoted these migratory behaviors, suggesting that Ezrin can inactivate NF2 tumor suppressor and promote metastasis." (PMID 37371090, 2023). "Ezrin and NHERF-1/2 are adaptor proteins that have diverse binding partners and facilitate the interaction of PODXL with the cytoskeletons of tumor cells." (PMID 38203331, 2023). "Ezrin and YAP1 are highly expressed in tumor cells, and Ezrin can regulate YAP1 expression, thereby promoting cancer occurrence and development." (PMID 37791063, 2023). "In addition, ezrin inhibition could dramatically decreased lung metastases, including decreased the incidence, lower percentage of micro-metastatic cells in lung tissues, as well as less circulating tumor cells (CTCs) in blood compared with vehicle." (PMID 35173550, 2022).
tumor (continued). "Evidence suggests that Ezrin is important in EMT by regulating and activating NF-κB, which has a critical role in promoting tumor progression and invasion." (PMID 35793608, 2022). "To identify putative tumor suppressors whose expression is downregulated in L1-expressing CRC cells, we blocked the L1–ezrin–NF-κB signaling pathway and searched for genes induced under these conditions." (PMID 36139637, 2022). "High ezrin expression in the primary tumor is an indicator of a short DFI, most likely due to ezrin's ability to facilitate lung colonization." (PMID 34660770, 2021). "An increased expression of ezrin and p-ERM was also demonstrated in vivo in HMPOS tumor tissue that metastasize to the lungs of mice 1 week after IT transplantation." (PMID 33807419, 2021). "PODXL, ezrin, and CLIC5 are colocalised in tumour regions of the rat liver, and PODXL and ezrin are present in immunoprecipitates of CLIC5." (PMID 34201212, 2021). "The modulation between Ezrin and E-cadherin is mediated by IL-1β and TGF-β1, suggesting that cytokine regulation in tumor invasion is governed by alteration in cell-cell interactions." (PMID 33240887, 2020). "In conclusion, our data identified ezrin as a determining effector molecule that cooperates with the NB tumor suppressor CHL1 in inducing neuronal differentiation and lower tumor aggressiveness." (PMID 33326488, 2020). "Another study in 2019 suggested the co-localization of CA9 with phosphorylated ezrin (EZR), activated the hypoxia–autophagy–EZR pathway in tumor-initiating human cells and primary CRC tissues, proving its clinical relevance." (PMID 32630086, 2020). "Regulatory mechanisms mediated by SNAIL crosstalk between AKT kinase, EZRIN, RHO-GTPase and miRNAs modulate tumor cell motility, adhesion and actin cytoskeleton organization, supporting the progression and metastasis of RMS (see the Graphical Abstract)." (PMID 32664538, 2020). "Direct inhibitors of ezrin, small molecules NSC305787 and NSC668394, demonstrated statistically significant reduction in tumor growth in vitro using the model of osteosarcoma." (PMID 32317857, 2020). "Blocking cancer cell dissemination by ezrin-targeted therapy could also be beneficial in certain neoadjuvant settings, where therapies such as surgery, chemotherapy, or radiation have been shown to induce cancer cell motility leading to higher numbers of circulating tumor cells." (PMID 30678714, 2019). "PRL-3 is over-expressed in the highly invasive HCT116 colon cancer cells, where it dephosphorylates ezrin at the C-terminal Thr567, as a means through which PRL-3 exerts its function in promoting tumour progression." (PMID 31382374, 2019). "We extracted data on demographics, treatment and primary malignancy and examined available tumor samples for MTA-1 and ezrin using immunohistochemistry (IHC)." (PMID 32039013, 2019). "From this cohort, we tested the predictive value of common clinicopathological parameters (ulceration, mitotic count and tumor regression) and FMNL-2, ezrin and BRAF V600E immunoreactivity, for sentinel node involvement and survival." (PMID 31039200, 2019). "Of the different tumor categories, DSS was longest in patients presenting with MSI / low ezrin tumors and shortest in MSS / high ezrin tumors." (PMID 28953975, 2017). "We first performed wound healing assays to examine tumor cell motility and found that the migratory ability of both DLD1 and LoVo cells was significantly reduced by transfection with ezrin siRNA compared with control siRNA." (PMID 29291001, 2017). "Although we observed co-localization of EZR, CLIC5 and PODXL in HCC samples, this expression pattern in tumor cells was only found in the late stage of HCC." (PMID 26135398, 2015).
tumor (continued). "The protein expression levels of EZR, CLIC5 and PODXL were higher in nodular and tumor areas compared to non-tumor areas or controls (p<0.05), which correlated with the qRT-PCR results." (PMID 26135398, 2015). "The expression of DPYSL3 mRNA was heterogeneous in each GC cell line, and it showed a significant correlation with known tumor promoting factors (VEGF, FAK and EZR)." (PMID 25096402, 2014). "Ezrin and p-ezrin (both Thr-567 and Tyr-353) proteins showed significantly higher levels in NSCLC samples compared with adjacent non-tumor and normal lung tissues." (PMID 24629131, 2014). "The percentages of strongly positive ezrin, ezrinThr-567 and ezrinTyr-353 cells were 40.7%, 45.3% and 48.0% in NSCLC, respectively, and were also significantly higher than in adjacent non-tumor tissues and normal tissue counterparts (P < 0.01)." (PMID 24629131, 2014). "Ezrin and p-ezrin protein expressions were examined by immunohistochemistry in 150 NSCLC and adjacent non-tumor tissues and 14 normal lung tissues." (PMID 24629131, 2014). "However, it remains unclear if ezrin plays a role in Src-induced tumour angio/lymphangiogenesis." (PMID 25231728, 2014). "Our findings further build on these models by suggesting a role for ezrin in the regulation of IL-6 expression and Stat3 activation leading to the upregulation of VEGF-A/-C and tumour angio/lymphangiogenesis." (PMID 25231728, 2014). "All antigens, and particularly EZR, VCL, VIM, PDC6I, hnRNPL and ANXA2 induced a specific antibody response in KC and KPC already at 1 to 3 months of age, when the tumor stage was limited to early PanIN." (PMID 24010981, 2013). "This association with HER2 was also observed in an immunofluorescence analysis of a histological section from a patient in which an architecturally disorganized, tumor lobule strongly co-expressed HER2 (green) and p-ezrin (red) at the membrane." (PMID 24086451, 2013). "Ezrin, a member of the ezrin/radixin/moesin (ERM) protein family, plays a pivotal role in tumor invasion and metastasis." (PMID 24182314, 2013). "In this report, we have shown that km23-1 depletion can block events known to be involved in cell invasion and tumor metastasis, such as activated ERK and high expression of Ezrin." (PMID 23755307, 2013). "Moesin (MSN), a member of the ezrin-rdixin-moesin family and Claudin7 (CLDN7), a tight junction protein, both play a role in tumor cell metastasis." (PMID 22272721, 2012). "Our results link WWP1 and ezrin to the Met receptor activity, providing a molecular basis to the role of ezrin and WWP1 in tumor progression." (PMID 22629406, 2012). "Among others, overexpression of serpin H1, F-actin capping protein subunit beta (CAPZB), macrophage capping protein (CAPG), villin 2 (EZR), and cathepsin B (CTSB) are known to promote cell motility and invasion in tumor tissues." (PMID 21305022, 2011). "Beyond clinical similarities such as tumor location and chemotherapy resistance, canine and human OSA share similar biologic features including early metastasis, dysregulated expression of ezrin, Met, and Her2/Neu, and overlapping transcriptional profiles." (PMID 19284568, 2009). "Liver tumour and adjacent non-tumour tissues were detected for the expression of Proline-rich tyrosine kinase 2 (Pyk2), focal adhesion kinase (FAK), ezrin and fibronectin at protein and/or gene levels." (PMID 17551499, 2007). "Histological analysis of various organ sites in animals with tumours transfected with empty pCB6 vector or wild-type ezrin (WTC4, WTC6) revealed massive tumour nodules in the lung, as well as occasional metastases in the small intestine (data not shown)." (PMID 15987432, 2005). "Meanwhile, genes positively correlated with CLDN4 in expression, such as ANXA2, EZR and ELF3, were also discovered in our study, which were also reported to play a role in tumour progression and might explain the role of CLDN4 in a way." (PMID 38629624, 2024).
tumor (continued). "PODXL enhances the extravasation through direct binding to ezrin, a cytoskeletal linker protein, which enables the transition of tumor cells from a non-polarized, rounded cell shape to an invasive extravasation-competent morphology." (PMID 38203331, 2023). "The functional enrichment analysis revealed that tumor cells, even under chemotherapy treatment, contain proteins involved in processes like migration, cytoskeleton locomotion, and cell adhesion (ICAM, plexin, IL-16, CD40, ARPs, and ezrin)." (PMID 36611989, 2023). "Ezrin directly interacts with α1B-AR through a polyarginine motif on the receptor’s C-tail, regulating α1B-AR recycling to the plasma membrane, implying that Ezrin has a broader role in GPCR trafficking to promote tumor progression." (PMID 37371090, 2023). "Ezrin expression was absent in 14 of the 49 tumor samples (29%), weak in 25 (51%), and moderate in 10 (20%)." (PMID 36142656, 2022). "We further explored whether the three candidate genes (COL5A2, ezrin, and VIM) were highly specific to clinical OS tumor origin." (PMID 35625426, 2022). "Ezrin stabilizes the multiprotein complex consisting of HER2, plasma membrane Ca2+-ATPase 2 (PMCA2), NHERF1, and HSP90 at the specialized membrane domain, which results in membrane retention of HER2 contributing to tumor progression." (PMID 35328667, 2022). "Further supporting a tumor-suppressor role for miR-22, oncogenes such as galectin-1 (LGALS1), ezrin (EZR), histone deacetylase 4 (HDAC4) tyrosine 3-monooxygenase/tryptophan 5-monooxygenase (YWHAZ), specificity protein 1 (SP1), and basigin (CD147) were reported to be hepatic targets of miR-22." (PMID 36139435, 2022). "Furthermore, miR-28-3p was found to indirectly downregulate EZR/ezrin in RMS, a key regulator of tumor metastasis." (PMID 36033507, 2022). "Although some candidate markers, such as Rab1, Rab18, and Ezrin which are elevated in HCC, were reported to promote HCC progression, the oncogenic or tumor-suppressive roles of other candidate proteins we found in HCC tissues remain unclear." (PMID 33888099, 2021). "Although, moesin and ezrin had been proposed to function as oncogenes in various tumor cell lines, their potential roles in RCC is not known." (PMID 34503512, 2021). "In the current study, there was no significant relation between ezrin expression and histopathological type, gender and tumor site." (PMID 32334457, 2020). "Moreover, ezrin is a downstream target of SMARCB1/INI1, regulator of chromatin remodeling, and potential tumor suppressor." (PMID 32317857, 2020). "CM from both tumor cell lines induced M2 polarization as shown by the increased expression of CD163, FN1, and IL10 mRNAs, and a dramatically reduced expression of these M2 markers was observed in the ezrin-depleted cells." (PMID 33086476, 2020). "As regard tumor size, no statistical relationship was found between ezrin expression and tumor size." (PMID 32334457, 2020). "Interestingly, significant differences between SO and RAO were detected in tumor expression of MTA-1 (p = 0.015) and ezrin (0.002) with all RAO samples having high MTA-1 and most SO samples having low ezrin expression." (PMID 32039013, 2019). "The results of the present study showed that ezrin expression was not correlated with tumor responses to chemotherapy." (PMID 31376222, 2019). "Interestingly, ezrin turned out to be a stronger DSS predictor than any of the clinipathological factors, apart from tumor perforation." (PMID 28953975, 2017).
tumor (continued). "While ezrin was also localized to the plasma membrane of tumor cells in both conditions, we observed very little evidence of ezrin-lined microlumens in the MCF-7-control condition." (PMID 26796961, 2016). "Higher ezrin expression was found in OC metastases compared to primary tumor or normal ovary, but histotype was not specified." (PMID 27622508, 2016). "Our data are consistent with some other models of metastatic and/or more aggressive cancers exemplifying tumor promoting genes like urokinase plasminogen activator (uPA), PAX3 and Ezrin that are less methylated and/or more highly expressed in the more aggressive cancer forms." (PMID 25586191, 2015). "Ezrin can directly interact with the cytoplasm of CD44 molecules, influence conformation of cytoskeletal protein and its distribution, change apoptosis of tumor cells, regulate cell-cell adhesion with extracellular matrix, and promote metastasis and proliferation of tumors." (PMID 25929323, 2015). "Ezrin can regulate cell signal transduction by Rho factor, tyrosine kinase receptor, and Ras-to-MAPK pathway and plays an important role in cell movement, proliferation, apoptosis, cell cycle, invasion, and metastasis of tumor cells." (PMID 25929323, 2015). "Phosphorylation of Tyr-353 in ezrin is regulated through the PI3-kinase/Akt pathway, and phosphorylation of Thr-567 depends on the p38 MAP-kinase activity, and these phosphorylation events promote tumor amplification, metastasis and invasion." (PMID 24629131, 2014). "Neither cytoplasmic nor membranous ezrin expression was prognostic in non-invasive (pTa, pT1) tumours (data not shown)." (PMID 25278252, 2014). "Membranous but not cytoplasmic ezrin was significantly reduced in recurrent compared to primary tumours (p < 0.001)." (PMID 25278252, 2014). "Membranous (p < 0.001) but not cytoplasmic ezrin expression was demonstrated to be significantly downregulated in recurrent compared to primary tumours." (PMID 25278252, 2014). "Loss of expression of the membrane-cytoskeletal linking protein ezrin was initially demonstrated to be associated with tumour progression and poor prognosis in patients with T1G3 tumours treated with non-maintenance BCG (n = 92)." (PMID 24885195, 2014). "Together, these findings support the requirement of ezrin in tumour-induced angio/lymphangiogenesis regardless of T, B, and NK cell status of host recipients." (PMID 25231728, 2014). "Interestingly, however, we observed a significant correlation between a decreased ezrin expression (BVS 0, 1, 2 versus BVS 3) and a positive PgR status in the tumour blood vessels (P = 0.028)." (PMID 23420497, 2013). "In addition, we observed a correlation between low ezrin expression and HER-2 over-expression in the tumour blood vessels." (PMID 23420497, 2013). "Indeed, recent studies have revealed that ezrin may have an important role in tumorigenesis, development, invasion, and metastasis, probably through regulation of adhesion molecules, participation in cell signal transduction, and signaling to other cell membrane channels in the tumor." (PMID 23357878, 2013). "This novel finding suggests that phosphorylation at a single tyrosine residue (Y477) on ezrin plays a critical role in local invasion of tumor cells, while having no detectable effect on primary tumor outgrowth." (PMID 22397367, 2012). "Comparison of gene expression profiles in paired metastatic and nonmetastatic tumour cell lines and tissue samples revealed a strong increase in ezrin expression in metastases from rodent mammary and human pancreatic and colorectal carcinomas." (PMID 15987432, 2005). "Ezrin expression was statistically significantly lower in the CGTH (p < 0.01) and FTC-133 (p < 0.05) cells than in NTHY cells, whereas Moesin expression was significantly higher in all tumor cell lines tested (p < 0.05 for FTC-133 and p < 0.01 for CGTH, 8505c, TPC-1 BcPAP)." (PMID 35328683, 2022).